MTOR (mechanistic target of rapamycin kinase)
Diseases named in the same sentence as MTOR in open-access papers (continued):
Sharing a sentence is not in itself a finding about the gene and the disease.
tumor (continued). "Hamartin (TSC1) and tuberin (TSC2), encoded by the tuberous sclerosis complex (TSC) genes, form a tumor-suppressor heterodimer which is implicated in PI3K-Akt signaling and acts as a functional inhibitor of the mammalian target of rapamycin (mTOR)." (PMID 24593867, 2014). "Immunoblotting indicated that both AKT and mTOR phosphorylation was decreased in the myeloma tumor tissues excised from C96-treated mice, which were consistent with MM tumor growth treated by C96." (PMID 25003534, 2014). "It has been previously shown that in some neoplasms mTOR is an upstream activator of HIF-1α protein, enhancing its gene transcription." (PMID 25166211, 2014). "The increased expression of pAkt and mTOR in tumor sections of HED mice support the upregulation of pro-tumor signaling leading to aggressive tumor growth." (PMID 25026276, 2014). "The phosphorylation of ribosomal protein S6 (p-S6) is widely used as an indicator of mTOR activity in human tumor specimens." (PMID 25057912, 2014). "CPT1C anti-correlates with mammalian target of rapamycin (mTOR) pathway activation, and promotes cell survival and tumor growth." (PMID 25229745, 2014). "Specifically in human HCC, mTOR activation correlates with tumor size, an aggressive phenotype and poor prognostic features." (PMID 25533006, 2014). "The anticancer activity of δ-tocotrienol and its oxazine derivatives were found to be associated with a reduction in PI3K/Akt/mTOR and/or MAPK activity in several types of tumor cells." (PMID 25140303, 2014). "One patient, in whom SEGA was removed subtotally, required several additional surgeries for regrowing tumor and eventually mTOR inhibitor was introduced with significant improvement." (PMID 25227171, 2014). "The PI3K/Akt/mTOR pathway is a critical regulator of tumor cell metabolism, growth, proliferation, and survival." (PMID 24418474, 2014). "High p-mTOR and positive p-ERK1/2 staining were both associated with a positive PgR status and low tumor grade." (PMID 24447434, 2014). "Activation of IGFR and PI3K/Akt/mTOR pathways has been shown to indicate rapid tumor progression and poor prognosis in HCC." (PMID 24387108, 2014). "AIs have also been reported to increase in vivo apoptosis significantly in combination with an mTOR inhibitor, thereby exhibiting an anti-tumor effect." (PMID 24410765, 2014). "The data presented here on RIF-1 and B16/BL6 tumours confirm these observations for the allosteric mTOR inhibitor everolimus, providing further evidence that ΔT1 reflects the number of remaining proliferating tumour cells following successful chemotherapy." (PMID 24528602, 2014). "EGFR-related downstream effects are mediated by the phosphatidylinositol 3-kinase (PI3K) - Akt signaling cascade, which promotes tumor cell growth and inhibition of apoptosis by activation of mTOR." (PMID 24593867, 2014). "Activated PI3K/Akt/mTOR signaling impedes tumor cell apoptosis, promotes proliferation, angiogenesis, invasion, and metastasis." (PMID 25005526, 2014). "Of relevance to PI3K/AKT/mTOR, recent reports showcase anti-tumour activity in vitro and in vivo upon combining rapamycin (mTOR inhibitor inhibitor) with PI-103 (dual PI3K/AKT inhibitor)." (PMID 25144531, 2014). "In vitro study has shown that mTOR inhibitors, together with cytotoxic agents, exhibit tumor cell killing activity." (PMID 25364442, 2014). "In this study, the change of p-mTOR expression was found to correlate with the change of tumor size." (PMID 25364442, 2014). "Deregulated translation is therefore increasingly appreciated as a target for the development of tumor therapeutics, yet translation-oriented therapies (e.g. rapamycin and its analogues) so far were focused mainly on the inhibition of mTOR." (PMID 24416388, 2014). "First, we analyzed the HC1/mTOR interaction because dynein participates in mTOR co-localization; we observed an increased co-localization of the targets in both tumor cell lines." (PMID 25479096, 2014).
tumor (continued). "Secondly, when PI3K/Akt/mTOR continues to be activated, tumor cells show antiapoptotic properties in the growth and treatment process." (PMID 24944709, 2014). "A total of 76 UBC samples with representative tumour and non-tumour (normal or hyperplasic urothelium) sections were evaluated for p-mTOR immunoexpression." (PMID 25202348, 2014). "Tumours also often exhibit hyperactive PI3-kinase/mTOR signalling, which enables them to resynthesise proteins quickly." (PMID 24909675, 2014). "eIF4E, which is an element of the mammalian target of rapamycin (mTOR) pathway, has been considered an important target for ribavirin anti-tumor activity." (PMID 25904822, 2014). "The inhibition rates of tumors in mTOR siRNA, cisplatin, and mTOR siRNA + cisplatin groups were 58.27%, 63.18%, and 76.70%, respectively, indicating that mTOR siRNA combined with cisplatin has the strongest inhibition of tumor growth." (PMID 24818169, 2014). "Temsirolimus is a specific inhibitor of mTOR and inhibits tumor angiogenesis by reducing synthesis of VEGF." (PMID 28326251, 2014). "mTOR is a conserved PI3K-related ser/thr kinase that plays a pivotal role in tumor growth as it funnels signals from both receptors and nutrients to activate cell growth." (PMID 25221930, 2014). "Oxidative stress damages lipids, proteins and nucleic acids, and induces activation of Akt/PI3K/mTOR signalling, promoting oncogenesis, and tumour progression, in EDBC." (PMID 25338520, 2014). "A small-scale immunohistochemistry staining analysis revealed that 33 out of 73 (45%) HCC patients had increased expression of total S6k which correlated with mTOR activation as well as tumor nuclear grade and tumor size." (PMID 24804240, 2014). "Numerous preclinical studies have demonstrated that targeting both the RAS/RAF/MEK and the PI3K/AKT/mTOR pathway is more beneficial in numerous tumor types." (PMID 25401499, 2014). "As a matter of fact, recent studies have suggested that autophagic cell death mediates anti-tumor ability by a number of mTOR inhibitors or AMP-activated protein kinase (AMPK) activators." (PMID 24416349, 2014). "As proof of principle, we show that the mTOR inhibitor rapamycin results in significant changes in tumor phenotype." (PMID 24311731, 2014). "The involvement of the IGF-1R/ mTOR pathway in tumor initiation and progression is supported by mounting experimental evidence." (PMID 25026290, 2014). "Impaired function of PTEN or its lack is reflected by overactivation of PI3K/AKT/mTOR pathway, leading to uncontrolled growth of the tumor." (PMID 24745019, 2014). "The apoptosis protein array was then used to explore potential mediators of anti-tumor activity of different drug combinations targeting the IGFR/AKT/mTOR pathway." (PMID 24387108, 2014). "Further investigations showed that miR-137 exerted its anti-tumour activity via inhibiting the AKT2/mTOR pathway." (PMID 24970808, 2014). "Tumors of animals harboring hamartin loss and KRAS (G12D) expression in lung epithelial cells revealed 1) reduced tumor latency, 2) an activation of mTOR and 3) a response to treatment with rapamycin with improved survival compared to KRAS alone mutant mice." (PMID 24593867, 2014). "Several recent studies show that UA exerts its anti-tumor role through inhibition of the mTOR signaling pathway, suggesting a potential mechanism underlying the beneficial effects of UA." (PMID 24740400, 2014). "Specific mTOR inhibitors promoted apoptosis and autophagy in polyploidy tumor cells and increased the efficacy of Aurora kinase inhibitors, confirming tumor metabolism as a viable point of therapeutic intervention against AML polyploidy tumor cells." (PMID 24904834, 2014). "This resulted in the increased activity of signaling pathways and transcription factors that enhance TMEM cell development, such as AMPK which negatively regulated mTOR and Foxo1, and resulted in enhanced anti-tumor activity of CD8+ T cells." (PMID 24904823, 2014).
tumor (continued). "The effector kinases in the mTOR pathway activation are AKT, ERK1/2 and ribosomal S6 kinase RSK1, which phosphorylates and inactivates tuberous sclerosis complex 1/2 (a tumour suppressor) and activates mTOR on serine 2448." (PMID 24376606, 2013). "For instance, Metformin, an anti-diabetic drug, which regulates cell metabolism and the AMPK/mTOR signaling, has been already selected as a candidate for tumor therapy." (PMID 23388203, 2013). "This in turn highlights crucial roles of the mTOR pathways, particularly the mTORC2 pathway, in controlling tumor growth as well as aspects of tumor malignancy such as invasion and metastasis." (PMID 24244675, 2013). "Together these findings underscore the importance of mTOR-targeted therapy in inhibiting both tumor angio- and lymphangiogenesis." (PMID 23815869, 2013). "The apoptosis-inducing mTOR inhibitor Torin-1 hindered growth, motility, invasion, and survival of CoCSCs in vitro, and suppressed tumor growth in vivo with a concomitant reduction in vessel formation." (PMID 24185040, 2013). "The mTOR inhibitor, everolimus, which is currently undergoing clinical trials, exhibited an anti-tumor effect in some cases of advanced HCC." (PMID 23922888, 2013). "As previously reported, mTOR activation increases cell proliferation, whereas the blockade of mTOR signalling by rapamycin analogues slows tumour growth and increases survival in the HCC xenograft model." (PMID 24376606, 2013). "In broader terms, it has also been reported that low NUMB mRNA expression array of various cell lines from tumor types treated with AKT/PI3K inhibitors correlates with resistance to PI3K/mTOR inhibition." (PMID 23300998, 2013). "Some studies have shown that components of Akt signaling, such as PI3K, mTOR, and Akt itself, positively regulate Notch signaling in cells ranging from murine fibroblasts and neurons to a variety of human tumor cells." (PMID 23342113, 2013). "The serine/threonine kinase mammalian target of rapamycin (mTOR) has been suggested as a crucial modulator of tumor cell growth and proliferation, and therefore a potential target for anticancer therapy." (PMID 24185040, 2013). "NVP-BEZ235, is a compound with dual PI3K/mTOR inhibitor activity, that acts as an ATP competitor and has been shown to significantly reduce tumor growth in a number of human xenograft models and PI3K driven lung models." (PMID 23935891, 2013). "Novel therapies targeting overexpressed proteins associated with tumor progression, such as ALK, PI3K, mTOR, Aurora, and tyrosine kinases are promising." (PMID 24396620, 2013). "In summary, metformin reduced the number and tumorigenicity of tumor-initiating HCC cells; however the involvement of the AMPK/mTOR pathway in its anti-tumor activity remains ambiguous." (PMID 23922888, 2013). "Here, we first analyzed metastatic CRC cells with the properties of intestinal stem cells as well as tumor-initiating cells for mTOR activation." (PMID 24185040, 2013). "It thus follows that tumor cells that have been “primed” to undergo autophagy by mTOR inhibition would be more likely to undergo increased cell death when autophagy is impaired." (PMID 23383069, 2013). "BEZ235 (Novartis) is an orally available PI3K/mTOR inhibitor that demonstrated efficacy in inhibiting tumor growth in preclinical mouse models." (PMID 24163230, 2013). "AKT/mTOR was involved in a number of important cellular processes including cellular survival and tumor metastasis pathways, which is frequently activated in RCC patients." (PMID 23690956, 2013). "Inhibition of the Src kinase activity abrogates induction of stellate morphology, activation of Akt and mTOR, and the expression of tumor promoting genes by TGF-β1 and Col-1." (PMID 23409704, 2013). "Using a dual PI3K/mTOR inhibitor, PF-04691502, we then showed that blockage of the PI3K/mTOR pathway inhibited the in vitro proliferation of CSCs and in vivo xenograft tumor growth with manageable toxicity." (PMID 23826249, 2013).
tumor (continued). "Mice challenged with p27-VEGF transfected tumor cells were more resistant to the antiangiogenic and apoptotic effects of the rapalog, temsirolimus, and active site mTOR inhibitor, pp242." (PMID 23533410, 2013). "CDDP (2 μmol/l) was used to assess the clinical value of the mTOR inhibitor in the treatment of the tumor and to test the synergistic inhibitory effect of the mTOR inhibitor on the growth of the cells in combination with a chemotherapy drug." (PMID 24179542, 2013). "MTOR activation increases cell proliferation, whereas the blockade of mTOR signalling by rapamycin analogues slows tumour growth and increases survival in the HCC xenograft model." (PMID 24376606, 2013). "Inhibition of mTOR, which is targeted by miR-101, led to reduced tumor growth in engrafted ALCL mouse models." (PMID 23431463, 2013). "A recent study has demonstrated that TAIII at the high concentrations (μM) is preferentially cytotoxic with respect to tumor cells via an inhibition of mTOR and an induction of ER stress, which is in agreement with our findings." (PMID 23878598, 2013). "AMPK mediates mTOR activation via AKT, which regulates tumor cell growth through the inhibition of the mammalian target of rapamycin (mTOR) pathway." (PMID 24146957, 2013). "As autophagy is required for the effective management of metabolic stress, promoting autophagy through mTOR pathway inhibition is reasonably expected to limit tumor progression." (PMID 23552851, 2013). "We show that the combination of dovitinib with the PI3K/mTOR inhibitor, NVP-BEZ235, strongly downregulates the FRS2/extracellular signal-regulated kinase (Erk) and PI3K/Akt/mTOR signaling pathways, resulting in high levels of apoptosis and tumor stasis." (PMID 23343422, 2013). "Our in vivo data demonstrated that ectopic VEGF rescued tumor from the antitumor effects of two different classes of mTOR inhibitors (temsirolimus and the “active site” inhibitor pp242)." (PMID 23533410, 2013). "Mice were therefore divided in two groups, and treated with 20mg/Kg Torin-1 or vehicle every day up to 12 days (parental tumor was confirmed for mTOR pathway activation before beginning Torin-1 treatment, data not shown)." (PMID 24185040, 2013). "mTOR inhibitors depress translation of several mRNAs specifically required for tumor cell cycle progression, proliferation, and angiogenesis suppressing oncogenesis." (PMID 23815869, 2013). "SRSF1 was able to promote Survivin protein translation in an mTOR-dependent manner, and was correlated with Survivin expression in tumour samples." (PMID 23592547, 2013). "More specifically, genes that inhibit autophagy, like mTor and Rheb, are upregulated in many tumours, whereas autophagy-promoting genes." (PMID 24216995, 2013). "The PI3K/Akt/mTOR pathway is activated in a number of human neoplasms, accompanied by lower overall and/or disease free survival." (PMID 23693095, 2013). "In many tumor types, the mTOR pathway is found activated through several different underlying mechanisms." (PMID 23785409, 2013). "Since mammalian target of rapamycin (mTOR) has been suggested as a crucial modulator of tumor biology, we aimed at evaluating the effectiveness of mTOR targeting for CRC therapy." (PMID 24185040, 2013). "Not only are genetic alterations identified and observed in preclinical models present in clinical samples, but there is also prognostic and potential therapeutic value in understanding how a patient’s tumor has a modified PI3K/AKT/mTOR pathway." (PMID 23591839, 2013). "NF1 is a tumor suppressor which has specific-Ras GTPase activating protein activity (GAP) by which it can regulate the mTOR pathway." (PMID 24260221, 2013). "Several PI3K/AKT/mTOR inhibitors were explored as single agents or in combination in clinical trials of different tumor types." (PMID 24036443, 2013). "mTOR inhibitors increase TF of tumor endothelial cells and vascular smooth muscle cells to induce tumor-specific thrombosis." (PMID 24403259, 2013).
tumor (continued). "The PI3K/AKT/mTOR signaling pathway plays an important role in regulating cell growth and proliferation of normal and tumor cells." (PMID 24287900, 2013). "The PI3K/AKT/mTOR pathway is constitutively-activated in many tumor types leading to enhanced tumor survival." (PMID 24392034, 2013). "In contrast, patient #4′s tumor was initially regulated primarily by the Akt/mTOR pathway, which explains his initial response to the therapy." (PMID 23922674, 2013). "Since this pathway is believed to largely drive the malignant behavior of several of these tumors, mTOR-inhibition is considered an attractive means to apply as anti-tumor treatment." (PMID 23785409, 2013). "It is possible that IL-24 inhibits the Akt/mTOR signaling pathway in endothelial cells akin to that observed in the tumor cells." (PMID 24377906, 2013). "Specifically, PI3K/AKT and mTOR pathways have been shown to play pivotal roles in tumor growth as they promote cell mass increase and cell cycle entry, counteract apoptosis, modulate cytoskeletal rearrangements, and enhance cell migration." (PMID 23533654, 2013). "Its role in inhibiting tumorigenesis is related to increased expression of AMPK that subsequently inhibits the action of mammalian target of rapamycin (mTOR) thereby inhibiting tumor growth and proliferation." (PMID 23975167, 2013). "Prior to testing 64Cu-NOTA-bevacizumab PET therapeutic response imaging, a cohort of mice was treated daily with RAD001, 10 mg/kg, or vehicle, to determine the rapalog’s effect on tumor mTOR signaling and VEGF content." (PMID 23516584, 2013). "Autophagy is induced by multiple anticancer agents, especially mTOR inhibitors, as a tumor survival-promoting mechanism." (PMID 23383069, 2013). "Recently, mTOR (mammalian target of rapamycin) has gained remarkable attention as a potential target in different tumor types, including hematological malignancies." (PMID 23573198, 2013). "The combination of dovitinib + NVP-BEZ235 causes tumor stasis and strong down-regulation of the FRS2/Erk and PI3K/Akt/mTOR signaling pathways." (PMID 23343422, 2013). "Therapies targeting MAPK and AKT/mTOR signaling are currently being evaluated in clinical trials for several tumor types." (PMID 23676467, 2013). "PTEN is a tumor-suppressor gene that inhibits the PI3K/AKT/mTOR pathway by cleaving a phosphate group from the PI3K-activated second messenger PIP-3." (PMID 23691130, 2013). "The phosphatidylinositol-3-kinase (PI3K) and mammalian target of rapamycin (mTOR) signaling pathways play a central role for many tumor types in tumor cell proliferation, motility, invasion, metabolism and survival." (PMID 24042258, 2013). "The mTOR pathway is activated, with the vast majority of tumor cells showing moderate expression of p-mTOR (Ser 2448) on the plasmalemmal and cytoplasmic compartments." (PMID 23922674, 2013). "The therapeutic efficacy of a clinical candidate drug PF-04691502, a potent dual PI3K/mTOR inhibitor, was further demonstrated in both cell-based assays and in the xenograft tumor model derived from CSCs." (PMID 23826249, 2013). "Since these tumors are dependent upon the PI3K pathway, we investigated the potential for tumor response by the targeting of this pathway with rapamycin, an mTOR inhibitor." (PMID 23593290, 2013). "The PI3K/AKT/mTOR is a diverse pathway that affects equally diverse aspects of tumor development, progression, and patient survival." (PMID 23591839, 2013). "New basic questions have therefore been raised, including the following: how do mammalian target of rapamycin (mTOR) inhibitors affect the development of specific immune cells that are most critical to produce an effective anti-tumour immune response?" (PMID 24565200, 2013).